ADAM12 (ADAM metallopeptidase domain 12)
Description:
Involved in skeletal muscle regeneration, specifically at the onset of cell fusion. Also involved in macrophage-derived giant cells (MGC) and osteoclast formation from mononuclear precursors (By similarity).
Synonyms: MLTN; MCMPMltna; ADAM12-OT1; CAR10; MCMP; MLTNA
Tractability: Small molecule: it belongs to a druggable protein family. Antibody: UniProt places it where antibodies can reach, with high confidence; its Gene Ontology location is reachable by antibodies, with high confidence; UniProt predicts a signal peptide or a membrane-spanning region; the Human Protein Atlas places it where antibodies can reach. PROTAC: a small molecule that binds it is known.
Target class: Metallo protease MAM clan; Metallo protease; Protease; Enzyme; Metallo protease M12B subfamily
Gene: Protein-coding gene on chromosome 10 (126,012,381 to 126,388,477, reverse strand). Ensembl gene ENSG00000148848.
Subcellular location: Cell membrane (Isoform 1); Secreted (Isoform 2); Secreted (Isoform 3); Secreted (Isoform 4)
Subcellular location (Human Protein Atlas): Plasma membrane; Predicted to be secreted
Pathways (Reactome):
Extracellular matrix organization: Invadopodia formation
Signal Transduction: Signaling by EGFR
Gene Ontology:
Molecular function: protein binding; SH3 domain binding; metalloendopeptidase activity; metallopeptidase activity
Biological process: positive regulation of angiogenesis; myoblast fusion; proteolysis
Cellular component: plasma membrane; extracellular region
Genetic constraint (gnomAD): Loss-of-function variants: 66 observed, 99.03 expected, observed/expected ratio (o/e) 0.67, 90% interval 0.55 to 0.82. The upper end of that interval is the gene's LOEUF score, 0.82, which puts it in group 3 of 6, group 1 being the genes least tolerant of losing a copy. Missense variants: 912 observed, 1,070 expected, observed/expected ratio (o/e) 0.85, 90% interval 0.81 to 0.9. Synonymous variants: 388 observed, 401.01 expected, observed/expected ratio (o/e) 0.97, 90% interval 0.89 to 1.05.
Homologues: Orthologues: chimpanzee ADAM12 (99% identical), macaque ADAM12 (95% identical), pig ADAM12 (85% identical), dog ADAM12 (84% identical), rabbit ADAM12 (83% identical), guinea pig ADAM12 (82% identical), rat Adam12 (82% identical), mouse Adam12 (81% identical), tropical clawed frog adam12 (63% identical), zebrafish adam12b (59% identical), zebrafish adam12a (44% identical). Paralogues in human: ADAM19 (43% identical), ADAM33 (35% identical), ADAM15 (34% identical), ADAM9 (31% identical), ADAM8 (30% identical), ADAM28 (27% identical), ADAM22 (25% identical), ADAM7 (25% identical), ADAM11 (24% identical), ADAM29 (24% identical), ADAM20 (24% identical), ADAM23 (24% identical), and 8 more.
Diseases named in the same sentence as ADAM12 in open-access papers:
ADAM12 is named in the same sentence as 165 diseases in open-access papers, as found by Europe PMC text mining. Sharing a sentence is not in itself a finding about the gene and the disease. The quoted sentences say what the papers report.
breast carcinoma (63 papers, 2006 to 2025). "ADAM12 expression has been associated with tumor progression and is considered a potential biomarker for breast cancer." (PMID 39235446, 2025). "In another study, it was implied that a breast carcinoma-associated mutation in ADAM12 modifies a prospective dileucine trafficking signal that can alter protein processing and cellular localization." (PMID 38317965, 2024). "In this study, we used a breast cancer model to examine the effects of radiation alone or in combination with estrogens on the expression of genes linked to cell motility, such as ADAM12, CYR61, FLRT2, SLIT2, VNN1, MYLK, MAP1B, and TUBA1A." (PMID 39596804, 2024). "Accordingly, inspecting urinary ADAM12 can be useful in the development of non-invasive prognostic and diagnostic tests for breast carcinoma and other cancers." (PMID 38317965, 2024). "It has been shown that loss of ADAM12 decreased breast cancer cell chemoresistance while its overexpression protected cancer cells from treatment, which further supports ADAM12’s potential to predict response to treatment." (PMID 37495855, 2023). "ADAM12 also has been recognized as one of the candidate cancer genes in a comprehensive mutational analysis on human breast cancer." (PMID 33507683, 2021). "Since a clear relationship between EMT gene expression and invasive potential of breast carcinoma cells has been well established, our observations indicate that co-expression of ZO-1 and ADAM12 is linked to invasiveness." (PMID 29765546, 2018). "The human ADAM12 gene is the most frequently somatically mutated ADAM in breast cancer, and four missense mutations, D301H, G479E, T596A, and G668A, have a significant impact on protein functionality in cancer cells." (PMID 25886595, 2015). "The association of ADAM12 with breast cancer aggressiveness is in accordance with the induction of metastasis in vivo by ADAM12-overexpressing breast cell lines and the association of ADAM12 with metastases in triple-negative breast cancer." (PMID 26407179, 2015). "Overexpression of ADAM12 in the Polyoma virus middle T antigen (PyMT) mouse model of breast cancer accelerates tumor progression, and ADAM12 deficiency delays PyMT-induced mammary tumorigenesis." (PMID 25886595, 2015). "Together, these data demonstrated that expression of ADAM12 is correlated with the expression of EMT markers in breast cancers and confirmed the association of ADAM12 expression with aggressiveness." (PMID 26407179, 2015). "The current study, together with two other previous reports, provides an insight into the structural/functional aspects of the currently known breast cancer-associated mutations in ADAM12." (PMID 24651654, 2014). "ADAM15 cytoplasmic domain variants have been implicated in mammary carcinoma, while an ADAM12 secreted isoform promotes breast tumor metastasis in vivo." (PMID 24375628, 2014). "Six different somatic missense mutations in the human ADAM12 gene have been identified so far in breast cancer." (PMID 24651654, 2014). "Among thirteen different ADAM genes that encode catalytically active proteases, ADAM12 is the most frequently somatically mutated gene in human breast cancers." (PMID 24651654, 2014). "Hs578T and MDA-MB-231 cell lines represent claudin-low breast cancer cell lines, in which high levels of ADAM12 transcript variant 1 were detected by microarray profiling." (PMID 24116070, 2013). "In an analysis of genomic changes in breast cancer, three somatic heterozygous mutations were found in ADAM12, p.D301H in the metalloprotease domain, p.G479E in the disintegrin domain, and p.L792F in the cytoplasmic domain." (PMID 22662180, 2012). "ADAM12 in breast cancer was among the first of ADAMs shown to have diagnostic potential." (PMID 33507683, 2021). "A recently identified breast cancer-associated mutation in the metalloprotease ADAM12 alters a potential dileucine trafficking signal, which could affect protein processing and cellular localization." (PMID 22662180, 2012).
breast carcinoma (continued). "One of the first ADAMs shown to have diagnostic potential was ADAM12 in breast cancer." (PMID 21906355, 2011). "Similarly, hypomethylation of ADAM12 promoter was linked with worse outcomes in breast cancer." (PMID 35571032, 2022). "Recent finding enlightened the differential role of the long and short forms of ADAM12 leading to the hypothesis that ADAM12L might be involved in the early-stage of breast cancer and ADAM12S might be rather implicated in the migration and invasion of cancer cell." (PMID 26407179, 2015). "Another study demonstrates that under hypoxic conditions, HIF-dependent upregulation of ADAM12 promotes breast cancer metastasis by enhancing HB-EGF shedding and activating EGFR–FAK signalling." (PMID 40427200, 2025). "We investigated the protein-level expression of the target gene ADAM12 modulated by miRNA30b in breast cancer cells." (PMID 39742357, 2024). "In other words, miRNA30b facilitated the malignant progression of breast cancer by downregulating the expression of ADAM12." (PMID 39742357, 2024). "ADAM12 is overexpressed in human breast carcinomas and is a chemoresistance prognosticator in estrogen receptor-negative cancers." (PMID 38317965, 2024). "Another study was designed to investigate the role of ADAM12 in developing the CSC phenotype in breast carcinoma cells." (PMID 38317965, 2024). "ADAM12 has also been found in the urine of breast cancer patients, with its protein levels being connected with cancer risk, stage, and disease status." (PMID 39596804, 2024). "Bioinformatics tools predicted that the target gene of miRNA30b is ADAM12, which has been reported to be overexpressed in many tumors, especially in breast cancer, and is thought to play an important role in carcinogenesis." (PMID 39742357, 2024). "ADAM12 induction is through epithelial-to-mesenchymal transition, a characteristic of claudin-low breast carcinomas that is congested with markers of cancer stem cells (CSC)." (PMID 38317965, 2024). "Based on the previous findings, this prompted us to study the effect of ADAM12 on ECM molecules in breast carcinomas, using an experimental mouse model." (PMID 38892056, 2024). "Altogether, these results implied that ADAM12 actively reinforces the CSC phenotypes in claudin-low expressing breast carcinoma cells by modulating the EGFR pathway." (PMID 38317965, 2024). "ADAM12 as a prognostic marker has been established in a variety of cancer types, including breast cancer, bladder cancer, lung cancer and ovarian cancer." (PMID 35413826, 2022). "In another study on 122 genes, it was found that this gene was mutated with high frequencies in breast cancers, there was only one ADAM gene, namely ADAM12 and the rest only 14 genes had a higher cancer mutation prevalence score than ADAM12." (PMID 33507683, 2021). "ADAM12 mRNA was overexpressed in tumor tissues, such as breast cancer, cervical cancer, CRC, and esophageal cancer." (PMID 34604068, 2021). "Breast cancer cases are commonly associated with raised levels of ADAM9, ADAM12, ADAM15, ADAM17, and ADAM28." (PMID 33507683, 2021). "ADAM12 belongs to the ADAMs family, which can promote cell invasion and metastasis in various cancers including esophageal cancer, colorectal cancer, breast cancer and prostate cancer." (PMID 34150667, 2021). "ADAM12 is participated in TGF-β mediated EMT in breast cancer, while ADAM17 induces EMT in colorectal cancer via Notch signaling pathway." (PMID 32637415, 2020). "In another study, lnc015192 was shown to sponge miR-34a to upregulate Adam12 expression in breast cancer." (PMID 31569404, 2019). "To demonstrate interdependency between the individual effects of ADAM12L and ZO-1, we take advantage of the breast cancer cell line BT549 that is characterized by lower ADAM12 levels than HS578T." (PMID 29765546, 2018).
breast carcinoma (continued). "Because we previously reported the association of ADAM12 expression with EMT signature, we performed a new clustering analysis of breast cancer cell lines based on the expression of EMT gene set from the Molecular Signatures Database." (PMID 29765546, 2018). "We validate the interaction between ZO-1 and ADAM12 in invasive breast cancer cell lines and show that ZO-1 and ADAM12 co-localize in actin- and cortactin-rich structures." (PMID 29765546, 2018). "In silico screening demonstrates that ZO-1 and ADAM12 are coexpressed in breast cancer cell lines sharing EMT signature." (PMID 29765546, 2018). "ADAM12 supports the CSC phenotype in claudin-low breast cancer cells via modulation of the EGFR activation." (PMID 28148288, 2017). "Among twelve catalytically active human ADAMs, ADAM12 possesses unique characteristics that make it an attractive candidate for future use as a target or a biomarker in breast cancer." (PMID 28148288, 2017). "ADAM12 expression is strongly elevated in most human breast cancers compared to normal mammary epithelium." (PMID 28148288, 2017). "To gain insight into global gene expression networks regulated by ADAM12 in breast cancer cells, we performed RNA sequencing of SUM159PT_shADAM12 and SUM159PT_shControl cells, before and after doxycycline treatment." (PMID 28148288, 2017). "These xenograft experiments clearly demonstrate that ADAM12 silencing can greatly improve the therapeutic efficacy of 5-FU in breast cancer." (PMID 28852196, 2017). "ADAM12 expression was downregulated in representative claudin-low breast cancer cell lines, SUM159PT and Hs578T, using siRNA transfection or inducible shRNA expression." (PMID 28148288, 2017). "ADAM12 is upregulated in human breast cancers and is a predictor of chemoresistance in estrogen receptor-negative tumors." (PMID 28148288, 2017). "ADAM12 is involved in a variety of biological processes involving cell-cell and cell-matrix interactions, and is also known as a potential drug target in breast cancer." (PMID 26700623, 2016). "For example, its gene expression was upregulated in breast cancer tissues, compared with that of normal tissues, and high levels of the ADAM12 protein were related with poor prognosis." (PMID 27557513, 2016). "We show that ADAM12 expression is correlated with EMT markers in human breast cancer cell lines and biopsies." (PMID 26407179, 2015). "Deregulated expression and activity of ADAM12 (A Disintegrin And Metalloproteinase 12) have been frequently observed in human breast cancer." (PMID 25886595, 2015). "We further showed that expression of ADAM12 is correlated with expression of EMT markers in human breast cancer samples and the presence of metastases." (PMID 26407179, 2015). "Using transcriptomic data from a large panel of breast cancer cell lines, we demonstrated that ADAM12 clustered with EMT gene signature suggesting that ADAM12 is a component of EMT protein networks." (PMID 26407179, 2015). "The combination of ADAM8 and ADAM12 activities measured in urine samples was shown to identify with 90% confidence breast cancer patients with invasive and metastatic disease." (PMID 24375628, 2014). "The same study found that the ADAM12 gene was hypermethylated and showed lower expression in Luminal B tumors than in other types of breast cancer." (PMID 24651654, 2014). "Although ADAM-12 is overexpressed in numerous tumors, ADAM-12 as a specific diagnostic marker has only been used for breast cancer." (PMID 24465799, 2014). "ADAM-12 is highly expressed in numerous cancers including breast cancer, liver cancer, stomach cancer, colon cancer and nervous system cancer." (PMID 24465799, 2014). "This resulted in the identification of two upregulated genes (DPEP1 and MMP11) as mutated in colon cancer and another three protease genes mutated in breast cancer (TMPRSS3, ADAM12 and MMP10)." (PMID 24243807, 2013).
breast carcinoma (continued). "Our examination of three different breast cancer cell lines indicates that the relative abundance of ADAM12-La and ADAM12-Lb is different in these lines." (PMID 24116070, 2013). "For example, in breast cancer ADAM12 (rank #153) and MAP3K6 (rank #205) were recently reported to be associated with breast cancer oncogenesis." (PMID 22952662, 2012). "As well as breast cancer, ADAM12 has also been found to be elevated in urine from patients with bladder cancer, compared with healthy control subjects." (PMID 21906355, 2011). "As with urinary levels of ADAM12 in breast cancer, serum levels of ADAM28 increased progressively with increasing disease stage." (PMID 21906355, 2011). "Using logistic regression analysis, the authors calculated that the predictive probability of the presence of breast cancer was ≥ 80%, when levels of ADAM12 exceeded 40 arbitrary units." (PMID 21906355, 2011). "Others have reported an overexpression of ADAM-12 in liver carcinomas, and its levels in urine from patients have been correlated with survival in breast cancer." (PMID 16495931, 2006). "Further studies in breast cancer identified ADAM12 as a regulator of angiogenesis." (PMID 40427200, 2025). "Additionally, in claudin-low breast cancer cells, ADAM12 was shown to maintain the cancer stem cell (CSC) phenotype through the modulation of EGFR signalling." (PMID 40427200, 2025). "Finally, we examined the expression pattern of ADAM12 and collagen type 5 in cDNA arrays from human cases of breast carcinoma." (PMID 38892056, 2024). "This implies that reducing ADAM12 levels alongside endocrine therapy could be a beneficial strategy in breast cancer treatment." (PMID 39596804, 2024). "Finally, we examined human breast cancer data of cDNA arrays and found a strong correlation between ADAM12 mRNA expression and the three chains of collagen type 5." (PMID 38892056, 2024). "Lnc015192 regulates miR-34a and subsequently targets Adam12 in breast cancer through a ceRNA mechanism, and studies have also shown that LncRNA BLACAT1 promotes glioma development by binding to miR-605-3p to regulate VASP expression and promote glioma development and progression." (PMID 36943627, 2023). "In addition, studies have suggested that the expression of ADAM12 is increased in bladder, colorectal, gastric, lung, and breast cancers and leads to poor prognosis." (PMID 36717944, 2023). "In addition, ADAM12 expression has been shown to be a prognostic marker in ER + breast cancer samples." (PMID 35177031, 2022). "In addition, ADAM12 is a direct target gene of miR-29b in human breast cancer cells and miR-29b downregulated ADAM12 expression in rat renal cells." (PMID 36498866, 2022). "In breast cancer, disintegrin and metalloproteinase domain-containing protein 12 (ADAM12) is one of the members of MMP family, which its overexpression could increase angiogenesis through epidermal growth factor receptor (EGFR)/STAT3/AKT in BC." (PMID 35499045, 2022). "ADAM12 was also highly expressed in breast cancer and could promote cell invasion, migration, and epithelial-mesenchymal transition." (PMID 34663825, 2021). "Given the induction by Pparγ1 of EphA2, Amphiregulin, Adam12 in the mammary tumors we sought to determine whether PPARγ1 directly interacted in the context of chromatin with these target genes." (PMID 33946495, 2021). "Furthermore, ZO-1 (a marker of tight junctions in epithelial cells) and ADAM12 (a marker of mesenchymal cell differentiation) are co-expressed and interact with each other in invasive breast cancer cells." (PMID 31921836, 2019). "Then, knockdown Adam12 and lnc015192 inhibited breast cancer cell migration, invasion, and EMT." (PMID 30781524, 2019). "Furthermore, miR-29b was also found to target a spliced variant of ADAM-12 (ADAM-12L) which was found to possess prognostic and chemopredictive properties in breast cancer." (PMID 30323900, 2018).